SERPINB2 (serpin family B member 2)
Diseases named in the same sentence as SERPINB2 in open-access papers (continued):
Sharing a sentence is not in itself a finding about the gene and the disease.
breast carcinoma (continued). "High expression of tumor cell-associated SerpinB2 facilitates breast cancer cell survival and metastasis by protecting breast cancer cells from death signals, promoting breast cancer cell migration ability, and enhancing macrophage recruitment into tumor tissues." (PMID 38956496, 2024). "There is a significant association between SerpinB2 levels and survival, with breast cancer cell-associated SerpinB2 being identified as an unfavorable prognostic indicator, although the exact mechanism remains unclear." (PMID 39456691, 2024). "Taken together, our results suggest that SerpinB2 deficiency leads to macrophages with more M1 and fewer M2 characteristics, resulting in an inhibitory effect on the growth and metastatic potential of mammary cancer." (PMID 38956496, 2024). "SerpinB2 deficiency alters the expression of multiple genes in mammary tumors, which might cause a delay in PyMT-induced mammary tumor progression." (PMID 35768767, 2022). "Also, K2-deficient breast cancer cells showed enhanced expression of two senescence markers, p21 and SerpinB2 ex vivo and in mouse tumor xenografts derived from these cells." (PMID 35936112, 2021). "Our hypothesis is supported also by literature in the context of cancer: SERPINB2 has been associated with increased survival in breast cancer patients." (PMID 26779252, 2015). "SerpinB2 may be a useful biomarker for assessing metastasis risk in breast cancer patients." (PMID 28427146, 2017). "In contrast, SerpinB2 expression by breast cancer cells significantly inhibits metastasis by inhibiting extracellular uPA." (PMID 38956496, 2024). "Our results confirmed that ASC-exos promoted the TOX, CD4, and LYZ1 expression and inhibited the Mettl7b and Serpinb2 expression in breast cancer tumors, which were significantly enriched in the Human T-cell leukemia virus 1 infection pathway." (PMID 38294569, 2024). "Further research is needed to fully understand the molecular mechanisms and clinical implications of the interplay between SerpinB2 and Th1/Th2 immune responses in breast cancer." (PMID 38956496, 2024). "The role of SerpinB2 as a prognostic marker in breast cancer progression or suppression remains controversial." (PMID 38956496, 2024). "To appreciate the clinical significance of SERPINB2 in breast cancer, we performed comprehensive bioinformatics analyses on a large cohort of breast tumor patients." (PMID 38741146, 2024). "The combination of low SerpinB2, high NOS2, and low CD206 expression was associated with good DFS in patients with breast cancer with LN metastasis (n = 272, HR = 0.5329, P = 0.0341)." (PMID 38956496, 2024). "Nevertheless, the precise function of SerpinB2 in vivo regarding breast cancer progression and metastasis remains uncertain." (PMID 38956496, 2024). "Although SerpinB2 expression was observed in diverse cell types, the significant role of SerpinB2 expressed in TAMs as well as tumor cells during mammary tumor development and progression remains poorly understood." (PMID 38956496, 2024). "The patterns and expression levels of SerpinB2 in the mammary tumors and stroma of PyMTWT and PyMTSB2−/− mice were analyzed." (PMID 38956496, 2024). "ANGPTL4, PIEZO2, SCNN1A, LTBP1, and SerpinB2 promote the survival of breast cancer cells in the brain microenvironment." (PMID 37108248, 2023). "miR-107 was shown to negatively regulate NEAT1 expression and regulate breast cancer progression through affecting the tumor development-associated genes, including TIMP-1, PDGF-A, SERPINB2, cyclin D1, CDK4, and CPA1A in breast cancer cells." (PMID 37310654, 2023). "The miR-200c/141 cluster upregulated SerpinB2 in the MDA-MB-231 breast cancer cell line, inducing cell metastasis, which partially explains the mechanism." (PMID 36091129, 2022). "This work provides insights into the biological functions and regulatory mechanisms of SerpinB2 in mammary tumors." (PMID 35768767, 2022).
breast carcinoma (continued). "In this context, the secretion of the protease SerpinB2 by breast cancer cells has been reported to be a key mechanism modulating the brain microenvironment." (PMID 34502091, 2021). "Altogether, considering the different steps that a breast cancer tumoral cell must undergo to metastasize in the brain, our work highlights the importance of zinc homeostasis in two of the steps: SerpinB2 production and cancer stemness." (PMID 34502091, 2021). "For example, in vivo experiments with breast cancer cell lines revealed a pro-metastatic function of SERPINB2, whereas the opposite was shown for lung cancer cells." (PMID 34116687, 2021). "In a more general view, SerpinB2 expression has been shown to be more frequently overexpressed in TNBC cells than in other breast cancer subtypes." (PMID 34502091, 2021). "SerpinB2 is overexpressed in different tumor tissues, correlates to poor prognosis in primary breast cancer and other solid tumors, and promotes tumorigenesis and metastasis." (PMID 32316552, 2020). "SerpinB2 was also correlated with increased metastatic potential and unfavorable outcomes in breast cancer patients." (PMID 31590453, 2019). "In aggressive breast cancers, the expression levels of positive regulators of SERPINB2, such as FOXL2 (Z-score = 2.863, p-value = 0.258) and ERK (Z-score = 3.346, p-value = 0.677), were activated." (PMID 30965654, 2019). "We found that miR-200c/141 cluster overexpression upregulated SerpinB2 in the MDA-MB-231 triple-negative (TN) breast cancer cell line." (PMID 28427146, 2017). "The present study demonstrates that SerpinB2 promotes miR-200c/141 cluster overexpression-induced breast cancer cell metastasis, and SerpinB2 overexpression correlates with increased metastatic potential and unfavorable outcomes in breast cancer patients." (PMID 28427146, 2017). "On the contrary, genes such as PDGF-A, SERPINB2, TIMP1, which have been associated to poor prognosis, invasion and metastases, were down-regulated in CPT1A silenced breast cancer cells." (PMID 26799588, 2016). "Therefore, understanding the intricate interplay among SerpinB2, SerpinE1 and uPA is crucial for unraveling their roles in breast cancer biology and developing targeted therapeutic strategies." (PMID 38956496, 2024). "The role of SerpinB2 in breast cancer growth and metastasis is complex and controversial because SerpinB2 may have both pro-tumor and anti-tumor effects." (PMID 38956496, 2024). "We generated SerpinB2-deficient MMTV-PyMT (SB2−/−;PyMT) mice by intercrossing SerpinB2-deficient (SB2−/−) mice with C57BL/6 strain background MMTV-PyMT (PyMT) mice widely used to study human breast cancer." (PMID 35768767, 2022). "The SerpinB2-deficient human lung cancer cell line H2030-BrM3 and human breast cancer cell line MDA231-BrM2 do not form brain metastases because the deleterious effects of SerpinB2 on the vascular attachment and survival of cancer cells are inhibited." (PMID 35768767, 2022). "Among these genes, the expression of SERPINB2 (PAI-2) has been demonstrated to be Ca2+-dependent and the expression of PAI-2 has been shown to correlate with prolonged overall and disease-free survival of breast cancer patients as well as sensitivity to treatment with tamoxifen." (PMID 35355564, 2022). "Likewise, miR-200c/141 cluster overexpression induced by SerpinB2 was shown to foster breast cancer cell metastasis." (PMID 33536459, 2021). "SerpinB2 was overexpressed in the TN breast cancer subtype as compared to the luminal subtype." (PMID 28427146, 2017).
breast carcinoma (continued). "In addition, transcription factors known as tumor suppressors or genes related to breast cancer including c-FOS, EGR1, ID2 and SERPINB2, as well as suppression of metastasis associated genes (CD44 and IL11) have emerged as molecular targets of BSP knockdown." (PMID 24980816, 2014). "The combination of SerpinB2, NOS2, and CD206 expression in tumor cells as well as TAMs and its clinical significance should be further evaluated in a cohort of patients with breast cancer." (PMID 38956496, 2024). "The combination of low SerpinB2, high NOS2, and low CD206 expression was favorable for survival in patients with breast cancer, as assessed in the BreastMark dataset." (PMID 38956496, 2024). "However, in SB2−/−;PyMT tumors, a high levels of IFN-γ, which activates the antitumor immune response, and a low levels of Anxa3, which controls cancer cell invasion and lung metastasis, do not support SerpinB2 deficiency causing a delay in PyMT-induced mammary tumor progression." (PMID 35768767, 2022). "Overexpression of the miR-200c/141 cluster, also a member of the miR-200 family, was found to upregulate SerpinB2, also known as plasminogen activator inhibitor type 2 or PAI-2, in the MDA-MB-231 breast cancer cell line." (PMID 32316552, 2020). "The analyses of the combinations of SerpinB2/NOS2, SerpinB2/CD206, and NOS2/CD206 groups, as well as the individual expressions of SerpinB2, NOS2, or CD206 alone did not demonstrate a significant difference in the DFS of patients with breast cancer." (PMID 38956496, 2024). "Additionally, an in vitro study revealed that knocking down SerpinB2 in MDA-MB-231 breast cancer cells and RAW264.7 macrophages decreased breast cancer cell migration and sphere formation and the pro-tumorigenic polarization of macrophages." (PMID 38956496, 2024). "The role of SerpinB2 in controlling TAM immune responses in mammary cancer development and progression has not been well studied." (PMID 38956496, 2024). "The abundant expression of SerpinB2 was observed in epidermal keratinocytes of PyMTWT mouse skin, but the tumor cells did not exhibit strong SerpinB2 staining, showing that tumor cells in PyMTWT-induced mammary tumors express very low levels of SerpinB2." (PMID 38956496, 2024). "There is a lack of studies analyzing the in vivo role of SerpinB2 in transgenic and knockout animal models of breast cancer." (PMID 35768767, 2022). "Finally, the urokinase-type plasminogen activator inhibitor SERPINB2 was elevated in response to BSP knockdown, which is known to be a factor of good prognosis in breast cancer patients." (PMID 24980816, 2014). "Based on co-culture studies with MDA-MB-231 and SerpinB2-knockdown RAW264.7 (RAW264.7-siSB2), we speculate that macrophage-produced SerpinB2 regulates the migration ability of breast cancer cells without substantially impacting proliferative activity, leading to increased metastasis." (PMID 38956496, 2024).
COVID-19 (13 papers, 2020 to 2025). A disease caused by infection with severe acute respiratory syndrome coronavirus 2. "Furthermore, marker genes for the MT1G-high non-alveolar macrophage Cluster 3 and the RGS1-high Cluster 6 matched those identified in BAL fluid of healthy controls and patients with COVID-19, while the SERPINB2-high Cluster 13 matched marker genes from BAL cells obtained in healthy and COPD lungs." (PMID 38132091, 2023).
lung cancer (13 papers, 1998 to 2023). A malignant neoplasm involving the lung. "In summary, as a novel finding, low SerpinB2 expression in lung adenocarcinomas was independently associated with reduced lung cancer specific survival in our cohort." (PMID 29207598, 2017). "Low expression of SerpinB2 was associated with reduced lung cancer specific survival (LCSS) in adenocarcinomas (p = 0.017), also in stage I (p = 0.031)." (PMID 29207598, 2017). "Notably, our finding that low expression of SerpinB2 is associated with reduced cancer specific survival is in line with previous lung cancer studies where low tumor cell expression of SerpinB2 was associated with nodal metastasis and tumor dissemination." (PMID 29207598, 2017). "Our findings support data from model studies that SerpinB2 (PAI-2) is an important regulator of lung cancer progression." (PMID 29207598, 2017). "SerpinB2, a component of the urokinase plasminogen activator (uPA) system, has been recognized as a biomarker for the progression and metastasis of lung cancer." (PMID 27558531, 2016). "Low SerpinB2 levels are correlated with high metastatic characteristics in human lung cancer cells, lymph node metastasis and poor prognosis in primary lung cancer." (PMID 27558531, 2016). "Although several reports have identified SerpinB2 as an important marker for lung cancer progression and metastasis, the relationship between SerpinB2 and EGFR-TKI resistance has not been clearly elucidated." (PMID 27558531, 2016). "SERPINB2, encoding plasminogen activator inhibitor type 2 (also known as PAI-2), is commonly expressed in many types of human cancer including lung cancer." (PMID 26338969, 2015). "Although these results did not provide direct evidence that the aberrant expression of SLC30A1, SERPINB2 and AKR1C1 in human lung cancer is caused by exposure to PM2.5, they did indicate a role in the development of lung cancer of these genes whose expression can be induced by PM2.5 organic extract." (PMID 26338969, 2015). "Along these lines, we utilized the natural antitumor compound YD to target AXL degradation which exhibits anti-proliferative activities against various human lung cancer cells by regulating AXL, SerpinB2, NNMT, and BMP422,39–42." (PMID 31043587, 2019). "Recently, SerpinB2, Neuroserpin and L1CAM were reported to be key drivers in experimental studies of lung cancer dissemination, with special focus on the biology of brain metastases." (PMID 29207598, 2017). "The analysis of SLC30A1, SERPINB2 and AKR1C1 levels in human lung specimens from the TCGA database also revealed the aberrant expression of these genes in lung cancer tissues compared with paired normal tissues." (PMID 26338969, 2015). "Depression of plasma miR-182 and miR-185 in subjects exposed to high levels of PM2.5 and overexpression of SLC30A1, SERPINB2 and AKR1C1 in human lung cancer tissues were detected." (PMID 26338969, 2015). "We further analyzed SLC30A1, SERPINB2 and AKR1C1 mRNA expressions in human lung cancer retrieved from the TCGA database." (PMID 26338969, 2015). "Increased expressions of SLC30A1, SERPINB2 and AKR1C1 were detected in human lung cancer." (PMID 26338969, 2015).
melanoma (13 papers, 2000 to 2022). A malignant, usually aggressive tumor composed of atypical, neoplastic melanocytes. "High SerpinB2 expression is noted in mouse melanoma cell line of B16 cells, and human melanoma cell line of M24met inhibiting metastasis." (PMID 35768767, 2022). "The overexpression of SerpinB2 in mouse melanoma cells has been reported to reduce the length of invadopodia-like structures while not affecting their initial formation, and this event consequently reduced the migration and invasion of cells." (PMID 27558531, 2016). "In contrast, stage II melanoma patients showed a positive and higher correlation coefficient (r = 0.91) between serpin peptidase inhibitors (SERPINB2 and SERPINB6) in comparison to stage IV melanoma patients (r = -0.61)." (PMID 22032772, 2011). "In addition, perivascular expression of SerpinB2 in C8161 human melanoma cells promotes brain metastasis." (PMID 35768767, 2022).
Obesity (13 papers, 2011 to 2026). Accumulation of substantial excess body fat. "Chronic inflammation, such as obesity, diminishes SerpinB2 expression in VAT macrophages in patients and mice, leading to the decline of this macrophage subset." (PMID 41680163, 2026). "Clinically, activation of the NAcSh Serpinb2+ neurons may provide a potential treatment strategy for anorexia or obesity." (PMID 39147933, 2024).
pancreatic cancer (11 papers, 2010 to 2024). "The inhibition of these pathways by SERPINB2 is thus beneficial, and consequently, high SERPINB2 expression is linked with reduced tumor growth, reduced metastasis, and prolonged survival in a variety of cancers, such as pancreatic cancer and HNSCC." (PMID 36982651, 2023). "SerpinB2 is expressed in a number of different tumors, and SerpinB2 expression in tumor tissues has been associated with favorable prognosis for a number of cancers including breast and pancreatic cancers." (PMID 24644264, 2014). "Interestingly, however, the detected SERPINB2 mutation is predicted to result in a stop and therefore the expression of a functional SERPINB2 protein would be lost in those PSCs in pancreatic cancer." (PMID 35941161, 2022). "SERPINB2 o verexpression inhibits the aggressiveness and metastasis of liver and pancreatic cancers." (PMID 37033662, 2023). "SERPINB2 overexpression inhibited invasiveness and metastasis in liver cancer and pancreatic cancer." (PMID 36497110, 2022). "Despite reports of SERPINB2 expression in human pancreatic cancers, RT-qPCR analysis of wild type and Dusp5−/− pancreata revealed very low levels of pancreatic SerpinB2 mRNA expression compared with levels seen in skin." (PMID 35418690, 2022). "These included upregulation SERPINB2, a known oncogene, and a decrease in TGFβ1 expression, a cytokine which may function under specific circumstances as a tumor suppressor in pancreatic cancer." (PMID 32513126, 2020). "Furthermore, a recent study has indicated that SERPINB2 may actually play a protective role in pancreatic cancer by restraining both aberrant remodelling of the extracellular matrix (ECM) and local invasion from primary tumours." (PMID 35418690, 2022). "While specific mutations (such as SERPINB2) might contribute to tumor biology in individual cases, it is also conceivable that most of the identified mutations represent passenger mutations that do not have functional effects in pancreatic cancer-associated PSCs." (PMID 35941161, 2022).
thrombosis (11 papers, 2010 to 2025). "Recently, dysregulation of the ANXA3, TNFAIP6, TXK, BACH2, and SERPINB2 genes has been associated with both arterial and venous thrombosis in the general population." (PMID 37035297, 2023). "In the meta-analysis that inspired this study, the association between BACH2 and SERPINB2 with arterial and venous thrombosis was weaker than that of the other genes." (PMID 37035297, 2023). "In addition to PAI-1, the serpin plasminogen activator inhibitor type-2 (PAI-2, also known as SERPINB2), regulates plasminogen activation in models of venous thrombosis." (PMID 31258531, 2019).
diabetes (10 papers, 2012 to 2026). "In this study, to elucidate the contribution of the SERPINB2 gene to the pathogenesis of diabetic kidney disease in the context of type 2 diabetes mellitus (T2DM), we selected four tag single-nucleotide polymorphisms (SNPs) for genotyping in a case-control study of Caucasians." (PMID 39456691, 2024). "This study examined whether specific variants in the SERPINB2 gene, encompassing four tag SNPs, are linked to the progression of type 2 diabetes mellitus and the development of diabetic kidney disease in the context of this type of diabetes mellitus." (PMID 39456691, 2024). "Mechanistically, interferon-γ elevation in diabetes induces Ikaros, a transcriptional suppressor, which binds to the SerpinB2 promoter and decreases SerpinB2 expression." (PMID 41680163, 2026). "Within their gene families SERPINA6, SERPINB2, and SERPINB8 have long been known as biomarkers for diabetes." (PMID 34178943, 2021).